MMP2 (matrix metallopeptidase 2)
Diseases named in the same sentence as MMP2 in open-access papers (continued):
Sharing a sentence is not in itself a finding about the gene and the disease.
glioma (continued). "Some studies have reported the expression of MMP-2 in human gliomas." (PMID 27051552, 2016). "Interestingly, we found similar results in our cohort of bevacizumab-treated glioma patients, with an increase of MMP2 and a decrease of MMP9 plasma levels during treatment before progression." (PMID 26921265, 2016). "However, MALAT1 had little effect on the expression of TIMP3 (data not shown), further indicating that the mechanism of MALAT1-suppressed glioma cell invasion is via downregulation of expression of MMP2 at the protein level." (PMID 26938295, 2016). "Other groups have reported that AP-1 mediates Bcl-XL-induced MMP-2 expression in glioma cells." (PMID 26621844, 2016). "MMPs, especially, MMP9 and MMP2 are overexpressed during glioma development." (PMID 27647142, 2016). "In this study, the combination of ethanolic extract from propolis and ethanolic extract of fresh-cut H. perforatum L. was proved the ability to reduce invasiveness of glioma cells through the inhibition of MMP2 and MMP9 secretion and suppression of cell migration." (PMID 27647142, 2016). "MMP2 is a protease highly expressed by glioma cells and facilitates cell invasion." (PMID 27713911, 2016). "We thus hypothesized that IL-6 was also involved in regulating MMP14 expression through the activation of MMP2 or MMP9 in glioma." (PMID 27613828, 2016). "In addition, in glioma patients, MMP2 plasma level significantly decreased at the time of progression." (PMID 26921265, 2016). "Immunohistochemical staining, western blot analysis and RT-qPCR revealed that the mRNA and protein levels of ATF3 and matrix metalloproteinase 2 (MMP2) were higher in the glioma than in the normal human brain tissues, and that their levels were proportional to the pathological grades." (PMID 25872784, 2015). "MMP-2 is a constitutive protein found in the normal brain cardiovascular systems and glioma." (PMID 26733793, 2015). "Interestingly, the treatment with the MMP2 inhibitor suppressed the invasion induced by the WNK2 silencing, suggesting the existence of a WNK2-dependent MMP2 activity, which is involved in the glioma invasion." (PMID 25596741, 2015). "Interestingly, CTX has been observed to inhibit the enzymatic activity of the matrix metalloprotease MMP-2 and to promote endocytosis of this metalloprotease in glioma." (PMID 25826056, 2015). "Similarly to CTX, BmKCTa is of potential interest as therapeutic agent against glioma and has also been found to bind to MMP-2." (PMID 25826056, 2015). "The objective was to elucidate the role of ATF3, maspin and MMP2 in the development of gliomas." (PMID 25872784, 2015). "We adopted immunohistochemistry assay to measure the expression of MMP-2 in glioma tissue." (PMID 26788112, 2015). "Thus, WNK2 promoter methylation and silencing in gliomas is associated with increased JNK activation and MMP2 expression and activity, thus explaining in part tumor cell invasion potential." (PMID 25596741, 2015). "If we assume that JNK is a general MMP2 inhibitor in gliomas, even patients with normal WNK2 expression treated with a JNK inhibitor would better benefit from the treatment, both because of the invasion inhibition, and by the enhancement of temozolomide cytotoxicity." (PMID 25596741, 2015). "Administration of Δ9-THC and JWH-133 inhibits MMP-2 expression in in vivo model of glioma." (PMID 25115386, 2014). "PAX6 suppresses glioblastoma cell growth, anchorage-independent growth and glioma angiogenesis as well as invasiveness of glioblastoma cell, via inhibition of matrix metalloproteinase-2 (MMP2) expression and vascular endothelial growth factor A (VEGFA) expression." (PMID 24454925, 2014). "Moreover, recent studies demonstrated that a number of cell cycle-related and invasion-associated genes are regulated by IGF-1R, including CCND1 and MMP-2/MMP-9 in human glioma and head and neck cancer, which function through MAPK and PI3K/AKT pathways." (PMID 24378652, 2014).
glioma (continued). "Invasion of malignant cells into nearby healthy brain tissue in glioma patients may be mainly mediated by matrix metalloproteinases MMP-2 and MMP-9 which exhibit elevated expression in tumor progression." (PMID 24672773, 2014). "MMP-2 is highly expressed in gliomas as compared to normal brain tissue." (PMID 24715095, 2014). "At the same time, in vitro co-culture experiments between human fetal astrocytes and human glioma cell lines (U251N and U87), indicate that soluble factors released by glioma cells cleave the MMP2 pro-enzyme to its active form, demonstrating the dynamic interaction between GBM and the stroma." (PMID 23596394, 2013). "However, there has been no currently available information about relationships between glioma cell characteristics and upregulated proteins, such as Bcl-w, MMP-2 and β-catenin." (PMID 23826359, 2013). "Various studies show that glioma and microglia cells both produce MMP-2 in vitro and in situ." (PMID 24023566, 2013). "However, MMP-2 is released as an inactive profrom by glioma cells (especially at the invasive tumor zone), and glioma cells themselves are unable to activate pro-MMP-2." (PMID 24023566, 2013). "Inhibition of MMP-2 expression has been found to reduce cultured glioma cell invasiveness." (PMID 25505565, 2013). "Migration of glioma cells is considered to be correlated with MMP-2 expression and activity." (PMID 23304519, 2012). "Among the MMPs, attention in human gliomas has focused on gelatinases (MMP2 and MMP9)." (PMID 22681957, 2012). "Glioma-exposed microglia release metalloproteinase MT1-MMP which activates a latent metalloproteinase 2 (pro-MMP-2) produced by glioma cells that promotes tumor invasion, as was shown using brain slices from MT1-MMP-deficient mice and in a microglia depletion model." (PMID 21901144, 2011). "Rapamycin can suppress glioma invasion by blocking the production of MMP-2 and MMP-9." (PMID 22219636, 2011). "Moreover, CsA treatment resulted in the reduced expression of mt1-mmp in glioma-infiltrating CD11b+ and overall down-regulation of the MMP-2 activity." (PMID 21901144, 2011). "Our results illustrated that the expression levels of MMP-2 and MMP-9 are associated with the pathological grades of the tumor, providing strong evidence that MMPs expression can be used as a criterion to determine the malignant phenotypes of gliomas." (PMID 23554622, 2010). "Glioma angiogenesis has being targeted by RNA-based inhibitors, which include short hairpin RNAs (shRNAs) and short interfering RNAs (siRNAs) against urokinase-type plasminogen activator and MMP-2 respectively." (PMID 20932320, 2010). "The glioma cells showed MMP-2 and MMP-9 gelatinase activities." (PMID 20587068, 2010). "The importance of VEGF and its receptors Flt1 and Flk1, along with ERK1/2 and MMP2 in glioma angiogenesis and the inhibitory effects of GLA on these proteins' expression suggested the possibility that angiogenesis could be modified in the GLA-treated tumours." (PMID 19292920, 2009). "Inhibition of MMP-2 in human glioma cell line U-87 results in a dramatic reduction in cell invasion, and induction of PKC activation in a D54 human glioblastoma cell line results in enhanced invasion through the activation of several metalloproteases including MMP-2." (PMID 18294404, 2008). "Therefore, we determined the activity of MMP-2 by gelatin zymography after 24 h incubation with 5 μM As2O3 and 10 μM berberine in C6 or U-87 glioma cells." (PMID 18294404, 2008). "Additionally, BmKCT, a scorpion venom peptide from Buthus martensii Karsch, specifically targets chloride channels in glioma cells and downregulates MMP-2 expression, thereby inhibiting proliferation, invasion, and migration of glioma cells C6 and U251 (glioma) cells." (PMID 40137887, 2025). "Conversely, GAL-3 and MMP-2 levels were not directly associated with the presence of glioma." (PMID 40512281, 2025).
glioma (continued). "Furthermore, we found that HSYA inhibited the proliferation, migration, and invasion of glioma U251 cells, and its mechanism may be related to the downregulation of the expression of MMP-2 and MMP-9." (PMID 39877386, 2024). "Notably, a recent study indicated that IGFBP2 may act as a stimulator of VM formation by upregulating MMP2 expression in glioma cells, indicating that activation of MMPs might be essential for VM formation in glioma." (PMID 36708044, 2023). "Importantly, in human glioma microarray specimens (n = 85, N095Ct01, Bioaitech), we found a positive correlation between L1 and MMP2/9 staining intensities in the glioma specimens, thus supporting the notion that MMP2 and MMP9 are involved in L1‐mediated glioma invasion." (PMID 36708044, 2023). "In addition, the expressions of SCIN, MMP2, and MMP9 were associated with glioma prognosis." (PMID 36291348, 2022). "In addition, the expression of SCIN was related to MMP2/9 in glioma." (PMID 36291348, 2022). "Additionally, we also evaluated the effect of CBX7 and CBX8 on the invasion ability of glioma cell cells by detecting invasion-related markers of matrix metalloproteinase 2 (MMP2) and MMP9, and further confirmed the corresponding phenotypes of glioma cells by scratch wound-healing assay." (PMID 36034290, 2022). "In addition, CCL2/CCL5, MMP-2, and MMP-9 have been implicated in TLR9-mediated glioma progression." (PMID 34715891, 2021). "Thus, we would like to clarify the role of MMP-2 in the TCE inhibition of glioma cells." (PMID 34832965, 2021). "Moreover, inhibition of MMP-2 abrogated glioma cell migration stimulated by TGF-β2." (PMID 33553142, 2020). "We found that honokiol inhibited NF-κB expression, while increasing that of E-cadherin, suggesting that honokiol may inhibit migration and invasion of glioma cells in part by inhibition of MMP2/9 expression, as well as attenuation of the NF-κB-mediated E-cadherin pathway." (PMID 30587839, 2018). "Moreover, the immunofluorescence images further confirmed the MMP-2 expression in C6 glioma cells." (PMID 30670934, 2018). "Univariate analysis indicated that MMP2 could predict glioma prognosis auxiliarily." (PMID 29733521, 2018). "SMC4 overexpression markedly promoted glioma cell migration and invasive capability in vitro, as well as tumorigenicity in vivo, which was involved in alteration of expression of the invasion-related gene MMP2, MMP9 and the proliferation marker Ki67, but SMC4 downregulation reduced it." (PMID 28287612, 2017). "Furthermore, the ambiguities raised by Debin’s work have now been cleared by the identification of MMP2 as the direct target of chlorotoxin and the glioma-specific chloride channel possibly as the CLC3 family of chloride channels and both targets co-localized and over-expressed in tumour cells." (PMID 26848686, 2016). "Moreover, Bcl-2 overexpression in glioma, neuroblastoma, melanoma, breast cancer, lung cancer, and vascular smooth muscle cells increases the expression and activity of MMP-2, MMP-9, and uPA." (PMID 26621844, 2016). "In addition, TGF-β2 has been shown to increase tumor invasiveness by upregulating MMP-2 expression in glioma cells and evidence from other cell lines suggests that TGF-β1 may be an even more powerful inducer of MMP-2 expression." (PMID 22190972, 2011). "Among MMPs, gelatinases MMP-2 and MMP-9 are the most extensively studied in various pathological conditions, such as diabetes, cardiovascular diseases, gliomas, and multiple cancers." (PMID 40724896, 2025). "The expression and activity of MMPs, particularly MMP-2 and MMP-9, are consistently elevated in aggressive gliomas, such as GBM, the most malignant form of glioma." (PMID 40265458, 2025). "The gelatinases, MMP-2 and MMP-9, are thus of particular interest as biomarkers in assessing the progression of gliomas." (PMID 40265458, 2025).
glioma (continued). "MMP-2 and MMP-9 are particularly involved in the angiogenesis of human gliomas, as their degradation of ECM components releases stored pro-angiogenic factors, such as VEGF." (PMID 40265458, 2025). "High levels of MMP-2 and MMP-9 have been consistently correlated with increased invasiveness in high-grade gliomas, underscoring their importance in tumor spread." (PMID 40265458, 2025). "Sevoflurane was found to suppress migration and invasion in glioma cells (LN229 and U251) by upregulating microRNA-34a-5p (miR-34a-5p) and downregulating MMP-2." (PMID 40265458, 2025). "Quercetin significantly reduces T98G and U87 glioma cell proliferation and migration by inhibiting STAT3 phosphorylation, primarily through the downregulation of two STAT3 target genes: cyclin D1 and MMP-2." (PMID 40733274, 2025). "The activation of PKC in non-invasive astrocytes increased their MMP-2 activity and invasiveness, highlighting PKC’s regulatory role in glioma invasion." (PMID 40265458, 2025). "IsocuB was found to inhibit glioma growth by suppressing PDK1, Bcl-2, PI3K-AKT, and MAPK signaling pathways, as well as the activation of MMP-2/9." (PMID 38835342, 2024). "Overexpression of MAGI1 can affect AKT, MMP2, and MMP9 and inhibit the invasion and migration of glioma cells." (PMID 39458959, 2024). "The results of this study suggest that the knockdown of TBC1D1 affects the downstream expression of MMP2 and MMP-9 and inhibits the invasiveness of glioma cells." (PMID 38189823, 2024). "Regarding ANG-2, its overexpression in human gliomas parallels an increase in LN-5, and this correlates with the upregulation of MT1-MMP and MMP-2, as well as the invasion of glioma cells." (PMID 39120324, 2024). "In C6 rat glioma cells, it was shown that JNK activity controlled the expression of both MT1-MMP and TIMP-2, which led to the activation of MMP-2 in these cells." (PMID 38984107, 2024). "Treatment with inhibitors against Src, EGFR, p38, PI3K, and Akt counteracted the radiation-induced MMP-2 upregulation and subsequently the invasion of mutant PTEN glioma cells in vitro." (PMID 39682088, 2024). "Inhibiting AKT using the inhibitor API-1 decreased MMP2 expression, suggesting that CK1 controlled MMP2 via the AKT pathway, enhancing glioma cell invasion." (PMID 38706905, 2024). "TMEM176A negatively regulates the invasive function of cells and it reduces the expression of MMP2, MMP9 in different types of tumors, such as glioma, colorectal, liver, and esophageal cancers." (PMID 38850316, 2024). "An increase in global PLD activity was shown to induce matrix metalloproteinase 2 (MMP2) secretion and glioma cell invasion." (PMID 38534921, 2024). "There was no significant change in the expression of E-cadherin, however, the expression of N-cadherin, MMP-2, and MMP-9 decreased, further indicating that the downregulation of TBC1D1 affected the MMP family and thus weakened the aggressiveness of gliomas." (PMID 38189823, 2024). "Likewise, the gene codifying for MMP2 has been identified as a novel oncogene in colorectal cancer, while increased MMP-2 activity is involved in an essential step for the metastatic progression of most cancers and also linked with a poor prognosis in multiple tumors, including glioma." (PMID 38607010, 2024). "Levels of pro-apoptotic proteins (including Bad and cleaved-caspase-9) were increased, while the expressions of anti-apoptotic markers(e.g., MMP-9, MMP-2, and Bcl-2) were decreased in PQR309-treated glioma models." (PMID 38555280, 2024). "Glioma M2-polarized macrophages induce glioma cell migration by the release of anti-inflammatory cytokines like TGF-β, the upregulation of MMP-2 and the suppression of TIMP-2." (PMID 38969910, 2024). "For example, Diaph1 knockdown suppress migration and reduces the expression of matrix metallopeptidase MMP2 and MMP9 in human glioma cells." (PMID 39010074, 2024).
glioma (continued). "Overexpression of chemokine receptor type 4 (CXCR4) has also been demonstrated to induce the expression of MMP2 to degrade ECM and promote glioma invasion and migration." (PMID 39458959, 2024). "MMP-2 and MMP-9 levels were reduced by the downregulation of B7-H6 expression in glioma and B-cell NHL." (PMID 39408655, 2024). "A number of TAM-secreted factors, including stress-inducible protein 1 (STI1), epidermal growth factor (EGF), TGF-β, and matrix metallopeptidase-2 (MMP-2), have been shown to enhance proliferation and invasiveness of glioma cells." (PMID 38254796, 2024). "Nobiletin (425 μM or 4 mg/ml) can inhibit the expression of MMP-2 and MMP-9 in glioma cells and reduce the motility, adhesion and invasion ability of glioma cells." (PMID 37932838, 2023). "In gliomas, CTX inhibits the expression of MMP-2 and to achieve maximal inhibition, a dual system that employs an anti-cancer drug entrapped in or conjugated to a nano-carrier, together with the conjugation of CTX is used." (PMID 37444498, 2023). "On the other hand, the exposition of glioma U87MG cells to 1% oxygen demonstrated an increase in HIF-1α and MMP-2 transcription with a rise in cell invasion and migration capacities." (PMID 38069210, 2023). "Jointly with matrix metalloproteinase-2 (MMP2), CCL5 regulates the migratory and invasive flow of glioma cells and consequently increases intracellular calcium levels as well as p-calcium/calmodulin-dependent protein kinase II (p-CaMKII) and p-AKT expressions." (PMID 36980182, 2023). "SPOCK1 was reported to be a regulator of the ECM and is crucial for maintaining the process of tumor ECM dynamic homeostasis through regulating the activities and expressions of MMPs such as MMP-2, MMP-3, and MMP-9 in glioma, liver cancer, and prostate cancer." (PMID 36766694, 2023). "A study on gliomas found that tivozanib, a pan-inhibitor of VEGF receptor, inhibits cathepsin B/uPA/MMP-2." (PMID 37398678, 2023). "The expression of MMPs, especially MMP2, and MMP9, is upregulated and correlated with progression, tumor aggressiveness, and poor prognosis in glioma." (PMID 37509289, 2023). "Mechanistic studies show that IGFBP2 stimulates glioma cell VM formation via CD144 and MMP2 up-regulation." (PMID 38012763, 2023). "ROBO1 knockdown suppressed the expression of matrix metallopeptidase 2 (MMP2) and matrix metallopeptidase 9 (MMP9), thereby inhibiting the invasive, migratory and VM-forming abilities of glioma." (PMID 36459288, 2023). "For instance, TLR9, MMP-2, MMP-9, and MMP-13 expression is upregulated, while TIMP-3 is downregulated under hypoxic conditions (1% oxygen for 24 h) in glioma U373MG and D54MG cells." (PMID 38069210, 2023). "Second, GAMs also secrete matrix metallopeptidase 2 (MMP2) and MMP9, which are able to breakdown matrix proteins, such as collagen and fibronectin, thereby enabling glioma cells to penetrate and invade the surrounding stromal tissues." (PMID 38130720, 2023). "Mechanistically, we then assessed the protein levels of VEGFA, MMP2, and MMP9 in glioma cells after treatment with the miR‐143‐3p inhibitor and/or MEK‐2206." (PMID 36708044, 2023). "Among these, MMP-2 and MMP-9 are important effector molecules that enhance glioma cell invasiveness by breaking down extracellular matrix (ECM) components such as collagen and elastin." (PMID 36969167, 2023). "DCs under MMP2 activation trigger the differentiation of immature CD4+ T cells into Th2 cells, thereby promoting glioma invasion." (PMID 36464889, 2023). "Glioma cells secrete MMP-2 in an inactive state, which requires cleavage to attain an active form, microglia express the enzyme that cleaves MMP-2, MT1-MMP." (PMID 37700840, 2023). "Calycosin inhibits TGF‐N‐cadherin, Snail, Vimentin, MMP‐2 and MMP‐9 and inhibits glioma cell invasion and migration in vitro using the glial cell lines U87 and U251 in a dose‐dependent manner." (PMID 37675821, 2023).